YWHAG (tyrosine 3-monooxygenase/tryptophan 5-monooxygenase activation protein gamma)
Diseases named in the same sentence as YWHAG in open-access papers (continued):
Sharing a sentence is not in itself a finding about the gene and the disease.
cervical cancer (3 papers, 2022 to 2024). A primary or metastatic malignant neoplasm involving the cervix. "In conclusion, this study found that low YWHAG expression is remarkably associated with the poor prognosis of patients with cervical cancer." (PMID 35795276, 2022). "YWHAG was highly expressed in cervical cancer and was associated with poor prognosis." (PMID 35795276, 2022). "The purpose of this study was to determine the role of tyrosine 3-monooxygenase/tryptophan 5-monooxygenase activation protein gamma polypeptide (YWHAG) in cervical cancer and explore the effect of Curcuma on cervical cancer and its possible mechanism." (PMID 35795276, 2022). "The results of this study showed that YWHAG was highly expressed in cervical cancer cells, and patients with high YWHAG expression had a poor prognosis." (PMID 35795276, 2022). "The TCGA database of cervical cancer showed a positive correlation between YWHAG and hypoxia-inducible factor-1 subunit alpha (HIF-1α) expression." (PMID 35795276, 2022). "YWHAG knockout resulted in the inhibition of the proliferation and invasion of cervical cancer cells." (PMID 35795276, 2022). "The analysis of the TCGA database showed that YWHAG was highly expressed in a variety of tumors, including cervical cancer." (PMID 35795276, 2022). "Second, the downstream pathway of YWHAG–HIF-1α interaction that regulates the radiotherapy sensitivity of cervical cancer needs to be further studied to improve the research results." (PMID 35795276, 2022). "The results showed that YWHAG was highly expressed in cervical cancer cells, and the survival of these patients was shorter." (PMID 35795276, 2022). "The effect of YWHAG on the prognosis of patients with cervical cancer was analyzed, and the results showed that high YWHAG expression in patients with cervical cancer was statistically significant (P < 0.05)." (PMID 35795276, 2022). "The results showed that compared with the NC group, the proliferation ability of the cervical cancer cells was weakened after YWHAG knockout." (PMID 35795276, 2022). "Consistent with previous studies, YWHAG, as an oncogenic gene, promotes the viability of cervical cancer cells." (PMID 35795276, 2022). "In this study, curcumenol inhibited the proliferation and invasion of HeLa and C33A cells and promoted the apoptosis of cervical cancer cells by targeting YWHAG." (PMID 35795276, 2022). "Therefore, low YWHAG expression can inhibit the proliferation and invasion of cervical cancer cells." (PMID 35795276, 2022). "In conclusion, YWHAG can inhibit the PPP in cervical cancer cells and reduce glucose uptake." (PMID 35795276, 2022). "We first analyzed relevant data in TCGA to clarify the role of YWHAG in cervical cancer." (PMID 35795276, 2022). "In addition, the effect of YWHAG on cervical cancer cells is exerted through its interaction with HIF-1α, which then affects the PPP." (PMID 35795276, 2022). "YWHAG expression in cervical cancer was confirmed using The Cancer Genome Atlas (TCGA) database." (PMID 35795276, 2022). "The combination of drugs may promote the apoptosis of cervical cancer cells through the YWHAG pathway." (PMID 35795276, 2022). "In the present study, the expression of metabolites in the PPP decreased in cervical cancer cells after YWHAG knockout, suggesting that YWHAG is a key gene in the pentose phosphorylation process, and its effect on cervical cancer cells may be realized through this pathway." (PMID 35795276, 2022). "Whether YWHAG also plays a role in cervical cancer, it still needs further study." (PMID 35795276, 2022). "YWHAG can interact with HIF-1α to affect the proliferation and invasion of cervical cancer cells." (PMID 35795276, 2022). "In sum, YWHAG interacted and was positively correlated with HIF-1α in cervical cancer cells." (PMID 35795276, 2022).
cervical cancer (continued). "Cervical cancer data from TCGA were analyzed, and the correlation between YWHAG and HIF-1α in cervical cancer samples was measured using a microarray platform to investigate the proteins interacting with YWHAG that inhibit the proliferation of cervical cancer cells." (PMID 35795276, 2022).
Epileptic encephalopathy (3 papers, 2021 to 2025). A condition in which epileptiform abnormalities are believed to contribute to the progressive disturbance in cerebral function. "Previously, eight YWHAG mutations have been identified in patients with epileptic encephalopathy (EE)." (PMID 33767733, 2021). "YWHAG mutations have been demonstrated to be associated with epileptic encephalopathy, and occasionally identified in patients with developmental disorders and autism." (PMID 33767733, 2021). "Previously, eight de novo YWHAG mutations have been identified in patients with epileptic encephalopathy (EE), including Glu15Ala, Arg57Gly, Arg57Cys, Asp129Glu, Tyr133Ser, Leu177Ile, Asn178Asp in one patient each, and Arg132Cys recurrently in five unrelated cases." (PMID 33767733, 2021).
schizophrenia (3 papers, 2016 to 2020). A major psychotic disorder characterized by abnormalities in the perception or expression of reality. "However, in line with our results, higher levels of expression of YWHAB, YWHAE, YWHAG and YWHAZ have been described in the brains of schizophrenia patients compared with controls." (PMID 32555255, 2020). "Moreover, an increased expression of SFN and decreased expression of YWHAB, YWHAE, YWHAG and YWHAQ mRNA have been reported in leukocytes of schizophrenia patients." (PMID 32545830, 2020).
Alzheimer disease (2 papers, 2022 to 2025). A progressive, neurodegenerative disease characterized by loss of function and death of nerve cells in several areas of the brain leading to loss of cognitive function such as memory and language. "Multiple 14-3-3 homologues, YWHAB, YWHAE, YWHAG and YWHAZ, were also found to be consistently upregulated in Alzheimer's disease." (PMID 40491829, 2025).
autism (2 papers, 2024). Persistent deficits in social interaction and communication and interaction as well as a markedly restricted repertoire of activity and interest as well as repetitive patterns of behavior. "Further insights were gained through protein-protein interaction analysis, which revealed that IGF1R initially interacts with the protein of autism susceptibility gene YWHAG." (PMID 39376742, 2024).
developmental and epileptic encephalopathy 56 (2 papers, 2021 to 2022). "Eleven variants in the YWHAG gene have been reported to cause developmental and epileptic encephalopathy 56 (DEE56) (# 617665) or autism." (PMID 36243722, 2022). "The YWHAG gene is one such gene that has been reported to cause developmental and epileptic encephalopathy 56 (DEE56)." (PMID 36243722, 2022).
developmental delay (2 papers, 2022 to 2025). "Mutations in YWHAG, which encodes the 14-3-3γ protein, result in a spectrum of symptoms that can include seizures, developmental delays, and behavioral challenges." (PMID 40896335, 2025). "Here, we report a heterozygous missense variant, c.170G > A (p.R57H), in the YWHAG gene that caused early-onset epilepsy and developmental delay in a Chinese family." (PMID 36243722, 2022). "Trio-based whole-exome sequencing revealed a heterozygous missense variant, c.170G > A (p.R57H), in the YWHAG gene, which was considered as the cause of early-onset epilepsy and developmental delay in this family." (PMID 36243722, 2022). "Here, we report a missense variant c.170G > A (p.R57H) in exon 2 of YWHAG, which caused early-onset epilepsy and developmental delay in a Chinese family." (PMID 36243722, 2022).
head and neck squamous cell carcinoma (2 papers, 2022 to 2024). A squamous cell carcinoma that arises from any of the following anatomic sites: lip and oral cavity, nasal cavity, paranasal sinuses, pharynx, larynx, and salivary glands. "To substantiate the prognostic significance of our model, we recruited a clinical cohort consisting of 20 patients with head and neck squamous cell carcinoma at various clinical stages to verify the expression of the four genes (CCND1, FTH1, YWHAG and TNFRSF12A)." (PMID 37882107, 2024).
liver cancer (2 papers, 2016 to 2021). An epithelial or non-epithelial malignant neoplasm that arises from the liver. "PTPRG-AS1 can be regarded as a miR-199a-3p “sponge” and significantly promote the occurrence of liver cancer by activating YWHAG expression." (PMID 34876904, 2021).
febrile seizures (1 paper, 2021). "In this study, using trios-based whole exome sequencing, we identified two novel YWHAG mutations in two unrelated families with childhood myoclonic epilepsy and/or febrile seizures (FS)." (PMID 33767733, 2021).
gout (1 paper, 2022). A condition characterized by painful swelling of the joints, which is caused by deposition of urate crystals. "The main corn silk compound, Mandenol, treated gout by targeting the Hippo signaling pathway through the CTNNB1, YWHAG, and YWHAZ proteins." (PMID 36276864, 2022). "Our PPI analysis showed that turmeric and corn silk influence gout through their impact on a complex biological network, including HSPA1B, HSP90AB1, STUB1, CTNNB1, YWHAG, and YWHAZ." (PMID 36276864, 2022). "Mandenol, the corn silk compound, had high activity when docking with the target YWHAG and good activity when docking with the CTNNB1 and YWHAZ targets, suggesting that Mandenol may be an essential corn silk compound for gout." (PMID 36276864, 2022). "The essential compound of corn silk is mandenol, which may target the hippo signaling pathway to treat gout through CTNNB1, YWHAG, and YWHAZ proteins." (PMID 36276864, 2022).
hepatitis C (1 paper, 2020). "We found that miR-101-3p negatively regulated YWHAG in the hepatitis C pathway, and that the Hippo signaling pathway promoted HCC." (PMID 33234725, 2020). "YWHAG was also up-regulated, which might inhibit hepatitis C replication within cells, as well as promote anti-apoptotic genes, pro-proliferation genes, cell contact inhibition and organ size control by the Hippo signaling pathway." (PMID 33234725, 2020).
infantile spasms (1 paper, 2022). A rare epilepsy syndrome characterized by onset of epileptic spasms in infants between 2 and 12 months of age, and rarely up to 24 months. "In addition, three out of 14 patients with deletions including HIP1 and YWHAG, but not MAGI2, had infantile spasms, excluding one patient whose seizure type was not specified." (PMID 35481155, 2022).
lung adenocarcinoma (1 paper, 2021). A carcinoma that arises from the lung and is characterized by the presence of malignant glandular epithelial cells. "The ToppFun FEA, relative to diseases, predicted a possible association of the RAC1, CFH and 5 of the 14-3-3 protein family genes, namely SFN, YWHAB, YWHAE, YWHAG and YWHAZ with lung adenocarcinoma." (PMID 35366267, 2021).
melanoma (1 paper, 2017). A malignant, usually aggressive tumor composed of atypical, neoplastic melanocytes. "Interestingly, the top two upregulated genes in melanomas from RHC were PRKAA1 (fold change=1.37, p=0.08) and PIK3C3 (fold change=1.23, p=0.09) while the top two downregulated were YWHAG (fold change=0.62, p=0.29) and CLN3 (fold change=0.77, p=0.3)." (PMID 28030792, 2017).
memory (1 paper, 2022). The activities involved in the mental information processing system that receives (registers), modifies, stores, and retrieves informational stimuli. "Previous studies reported that cocaine exposure dysregulated the expression of YWHAG, and reduced YWHAG can lead to neuronal hyperexcitability, and normalization of hyperexcitability can rescue memory deficits." (PMID 35493321, 2022).
metastatic cancer (1 paper, 2023). A carcinoma which has spread from the original site of growth to another anatomic site. "To conclude, we elucidated a YWHAG regulome that coordinates gene regulatory networks for EMT‐associated processes in metastatic cancer cells." (PMID 37759388, 2023). "The YWHAG interactome also represents a novel target space for protein‒protein interaction (PPI) modulators in metastatic cancer." (PMID 37759388, 2023).
metastatic tumors (1 paper, 2023). "Finally, patients’ metastatic tumors had consistently elevated expression of YWHAG and autophagic proteins compared with lower‐grade tumors." (PMID 37759388, 2023).
myoclonic epilepsy (1 paper, 2021). A group of epilepsy syndromes in which myoclonic seizures are a prominent feature. "Two YWHAG mutations were identified in two unrelated families with childhood myoclonic epilepsy and FS, including a familial case with six individuals affected and a sporadic case with de novo mutation." (PMID 33767733, 2021). "In this study, two novel YWHAG mutations were identified in two unrelated families with childhood myoclonic epilepsy and FS, including a familial case with six individuals affected and a case with de novo mutation." (PMID 33767733, 2021). "This study suggests that YWHAG is potentially a candidate pathogenic gene of childhood myoclonic epilepsy and FS." (PMID 33767733, 2021). "Previously, myoclonic seizures and FS have also been observed in severe EE cases with mutations Glu15Ala and Arg132Cys, consistent with the observation in this study and supporting the association between YWHAG mutations and myoclonic epilepsy/FS." (PMID 33767733, 2021). "These evidences indicate that YWHAG mutations are potentially associated with mild phenotypes like myoclonic epilepsy and FS with favorable outcomes." (PMID 33767733, 2021).
cancer (28 papers, 2011 to 2026). A tumor composed of atypical neoplastic, often pleomorphic cells that invade other tissues. "Our data reveal that autophagy is a pivotal process for cancer metastasis, and YWHAG deficiency dismantles the EMT‐associated network and ceases these processes." (PMID 37759388, 2023). "It is demonstrated that a YWHAG‐dependent cytoprotective mechanism in the regulome is embedded in EMT‐associated networks to protect cancer cells from oxidative catastrophe through enhanced autophagy during EMT." (PMID 37759388, 2023). "We further demonstrate that a YWHAG‐dependent cytoprotective mechanism is embedded in EMT‐associated networks that protect cancer cells from oxidative catastrophe by YWHAG interaction with macroautophagic machinery and enhancing autophagy." (PMID 37759388, 2023). "The results suggest that the loss of YWHAG functionality in the presence of EMT inducers is potentially detrimental to cancer cells, highlighting a pivotal role for YWHAG in orchestrating many networks involved in EMT‐associated processes." (PMID 37759388, 2023). "YWHAG, which functions as a tumor suppressor in various cancers and encodes 14-3-3 protein gamma, was identified as the downstream target of miR-182." (PMID 37438760, 2023). "YWHAG encodes a protein as a scaffold in multiprotein complexes in cancer cellular processes." (PMID 36834736, 2023). "Next, we suppressed YWHAG using SMARTpool ON‐TARGETplus siRNA in three cancer cell lines, MKN74siYWHAG, MCF7siYWHAG, and HepG2siYWHAG." (PMID 37759388, 2023). "The cellular kinome and transcriptome data are surveyed to construct the regulome of YWHAG, revealing stress responses and metabolic processes during cancer EMT." (PMID 37759388, 2023). "Comparably, studies of overall survival, relapse‐free survival or disease‐specific survival harmoniously illustrated that patients with high YWHAG‐expressing cancers had worse prognoses (HRs of 1.26‐58.02)." (PMID 37759388, 2023). "The regulome of an oncogenic adaptor protein, tyrosine 3‐monooxygenase/tryptophan 5‐monooxygenase activation protein gamma (YWHAG), is integral to initiate and maintain cancer epithelial‐mesenchymal transition (EMT)." (PMID 37759388, 2023). "Tumor allografts show that metastasis potential and overall survival time are correlated with the YWHAG expression level of cancer cell lines." (PMID 37759388, 2023). "Conceivably, the deliberate activation of autophagy in YWHAG‐knockdown cancer cells during EMT would reduce cell death." (PMID 37759388, 2023). "Taken together, these observations suggest that YWHAG enhances autophagy to lessen oxidative stress‐related damage and improve the survival of cancer cells undergoing EMT." (PMID 37759388, 2023). "YWHAG deficiency exacerbated the effect of excessive oxidative stress on reduced cell viability, suggesting a YWHAG‐dependent cytoprotective mechanism against oxidative catastrophe during EMT in cancer cells, which is an energy‐demanding process." (PMID 37759388, 2023). "The suppression of YWHAG markedly delayed EMT in cancer cells, as suggested by a reduced Euclidean distance between cells and a reduction in mesenchymal‐associated genes and transcription factors with an increase in epithelial‐associated markers." (PMID 37759388, 2023). "Suppression of YWHAG by upregulating miR-182 resulted in increased cell proliferation and metastasis with increased cancer cell invasion, indicating miR-182 as a promising target for ESCC." (PMID 37438760, 2023). "Curcumenol inhibited YWHAG and increased the sensitivity of cisplatin chemotherapy and cancer cell apoptosis." (PMID 35795276, 2022). "Validation of the YWHAG expression level in different cancer stages from TCGA data showed higher expression levels of YWHAG in the advanced stage than in the early stage." (PMID 31959150, 2020). "We used the Cancer Genome Atlas (TCGA) data visualization web tool GEPIA to analyze the expression of YWHAG in normal and cancer tissues." (PMID 31959150, 2020).